CD4 (CD4 molecule)
Diseases named in the same sentence as CD4 in open-access papers (continued):
Sharing a sentence is not in itself a finding about the gene and the disease.
lupus vulgaris (1 paper, 2025). A form of cutaneous tuberculosis. "Concerning Lupus vulgaris, the patient with low CD4 count and high viral load had a positive TB culture and Ziehl–Neelsen stain." (PMID 40385314, 2025). "Lupus vulgaris generally occurs in individuals with moderate-to-high immunity; however, mucosal TB occurs at low CD4 counts." (PMID 40385314, 2025).
lymph node disease (1 paper, 2014). "In a US study of HIV positive adults with EPTB, there was a significantly increased risk of central nervous system, meningeal or disseminated TB disease compared to lymph node disease in those with severe immunosuppression (CD4 <100 cells/mm3)." (PMID 24564453, 2014).
lymph-node tumour (1 paper, 2003). "High numbers of infiltrating CD4+ and CD8+ T cells correlated with decreasing tumour invasion, and high numbers of infiltrating DCs correlated with decreasing lymph-node tumour metastasis." (PMID 14583778, 2003).
Lynch syndrome (1 paper, 2022). An autosomal dominant hereditary neoplastic syndrome characterized by the development of colorectal carcinoma and a high risk of developing endometrial carcinoma, gastric carcinoma, ovarian carcinoma, renal pelvis carcinoma, and small intestinal carcinoma. "Genome-wide bisulfite DNA sequencing data were generated using DNA from CD4 + T-cells obtained from peripheral blood using 27 patient samples from Lynch syndrome families." (PMID 35246124, 2022).
macrocytic anemia (1 paper, 2019). Anemia that is characterized by increased red blood cell volume. "There were no age, sex, baseline CD4 and baseline weight-related differences in the onset of macrocytic anemia over 18 months." (PMID 30935133, 2019). "Macrocytic anemia did not predict a post-enrollment change in CD4, BMI or QOL during follow-up." (PMID 30935133, 2019).
malocclusion (1 paper, 2025). "Furthermore, malocclusion resulted in a more substantial decrease in CD4+, CD8+, and naïve T cells." (PMID 40076520, 2025).
Microalbuminuria (1 paper, 2020). "Several studies have shown microalbuminuria being associated with reducing CD4 + counts." (PMID 33081706, 2020). "Microalbuminuria was highly prevalent in adult HIV − infected ART naive patients especially those with low CD4+ count." (PMID 33081706, 2020).
microcephaly (1 paper, 2023). A congenital or acquired developmental disorder in which the circumference of the head is smaller than normal for the person's age and sex. "In brain tissue biopsies from fatal cases of children born with microcephaly, there was an intense inflammatory infiltrate with an increased expression of CD4 T and CD8 T lymphocyte markers." (PMID 37376620, 2023).
Mikulicz's disease (1 paper, 2022). "In Mikulicz's disease, the affected gland tissue shows infiltration of CD4+ T helper cells and CD8+ CTLs." (PMID 35769404, 2022). "On comparing Mikulicz's disease patients with healthy individuals, CD4+GATA3+ Th2 cells are predominant and significantly increased in the affected salivary glands of Mikulicz's disease patients." (PMID 35769404, 2022).
mineralocorticoid excess (1 paper, 2015). "In previous studies of mineralocorticoid excess we showed that CXCR4 antagonism attenuated the accumulation of CD4+ T-lymphocytes." (PMID 26214690, 2015).
minimal change disease (1 paper, 2014). "This study is aimed at examining the frequencies of different subsets of CD4+CXCR5+ TFH cells in adult patients with minimal change disease (MCD)." (PMID 25243187, 2014).
Morton Neuroma (1 paper, 2025). Swelling and inflammation of the nerve between the ends of the metatarsal bones at the base of the toes. "CD4+ helper T cells were lower in patients with Morton's neuroma." (PMID 39588776, 2025).
Moyamoya disease (1 paper, 2023). Moyamoya disease (MMD) is a rare intracranial arteriopathy involving progressive stenosis of the cerebral vasculature located at the base of the brain causing transient ischemic attacks or strokes. "In immune cells, the occurrence and development of moyamoya disease may be related to the imbalance of the ratio of initial B cells, initial CD4 cells, resting natural killer cells, and regulatory T cells." (PMID 37153657, 2023).
MRSA pneumonia (1 paper, 2013). "In order to better characterize the effect of IR and MRSA pneumonia on different subsets of immune cells, splenocytes were isolated and stained for CD4 T cells, CD8 T cells, B cells, NK cells, dendritic cells, and macrophages." (PMID 24204769, 2013).
mucinosis (1 paper, 2004). "Interestingly, immunohistochemistry also revealed a number of CD4+ and CD20+ dermal inflammatory lymphocytes as well as anti-human mast cell tryptase+ cells, which may profoundly contribute to mucinosis formation." (PMID 15385052, 2004).
mucinous ovarian carcinomas (1 paper, 2023). An invasive malignant neoplasm that arises from the ovary and is characterized by the presence of malignant epithelial cells that contain intracytoplasmic mucin and may resemble the epithelial cells of the endocervix or gastrointestinal tract. "In mucinous ovarian carcinomas, CD4+ and CD8+ TILs were expressed at higher levels in the stroma compared to the epithelium." (PMID 37761986, 2023).
Mycobacterium avium complex (1 paper, 2015). "This greater prevalence could be, at least in part, due to the use of macrolides in the chemoprevention of Mycobacterium avium complex (MAC) infection in severely immunocompromised HIV patients (CD4 counts <100)." (PMID 26691198, 2015).
myxoma (1 paper, 2024). A benign soft tissue neoplasm characterized by the presence of spindle and stellate cells, lobulated growth pattern, and myxoid stroma formation. "Conversely, in myxoma, the transition mainly involves T_CD4 + _C2, with upregulated genes associated with cytokine production during this process." (PMID 39090109, 2024).
Narcolepsy type 1 (1 paper, 2023). "Narcolepsy type 1 (NT1) is caused by a loss of hypothalamic orexin-producing cells, and autoreactive CD4+ and CD8+ T cells have been suggested to play a role in the autoimmune mechanism." (PMID 37380713, 2023).
necrosis (1 paper, 2025). The phenotypic observation that death has occurred in groups of cells or in one or more tissues due to external factors, such as infection, toxins, mechanical trauma, loss of blood supply and other injuries (e.g. corrosion or burning). "Additionally, the reduction in lymphocytes and specific CD4 counts is correlated with a low ejection fraction, high degree of myocardial necrosis, and mortality rate in AMI patients." (PMID 40662135, 2025).
neuralgia (1 paper, 2020). "The median of patients with HZN and neuralgia without HZN of age, NRS score, percentage of CD8+, CD4+/CD8+, IL-6, and galectin-3 were 63.0, 5.0, 29.0, 1.25, 49, and 1.005, respectively." (PMID 32351643, 2020).
neuroendocrine disorder (1 paper, 2019). A disease or disorder that affects the neuroendocrine gland, any of the organized aggregations of cells that function as secretory or excretory organs and that release hormones in response to neural stimuli. "Individuals with Cushing’s disease, a neuroendocrine disorder characterized by over-production of adrenocorticotropic hormone (ACTH) and therefore cortisol, display immune impairments, such as decreased CD4+ populations, which we also observed in singly housed HU mice." (PMID 31572207, 2019).
neurofibroma (1 paper, 2017). An intraneural or extraneural neoplasm arising from nerve tissues and neural sheaths. "We found that MPNST tumors contain much higher numbers of CD8+, CD4+, CD56+, and CD45RO+ lymphocytes overall than those observed in the neurofibromas." (PMID 29137242, 2017).
nicotine addiction (1 paper, 2025). "In addition, several pathways indicative of interactions between the immune function of CD4 T cells and neuromodulatory function (dopaminergic synapse, glutamergic synapse, nicotine addiction) were identified." (PMID 40733683, 2025).
Nijmegen breakage syndrome (1 paper, 2025). Nijmegen breakage syndrome is a rare genetic disease presenting at birth with microcephaly, dysmorphic facial features, becoming more noticeable with age, growth delay, and later-onset complications such as malignancies and infections. "Three infants were diagnosed with Nijmegen breakage syndrome, all of whom demonstrated persistently low TREC/KREC levels across two DBS samples, accompanied by decreased CD3, CD4, and CD19 counts." (PMID 41459527, 2025).
NK-/T-cell lymphoma (1 paper, 2022). "Out of the 3 SPTCL, one was reclassified as NK-/T-cell lymphoma (NKTCL), and the other case had polyclonal mixed CD4 and CD8 T-cell population on FCI in FNA from the subcutaneous nodule." (PMID 35299754, 2022).
nodular melanoma (1 paper, 2024). "Most cases with a high H-score of 31, corresponding to nodular melanoma, showed the predominance of CD8+ cells in the TME, while the other 10 showed a predominance of CD4+ cells." (PMID 38673920, 2024).
nut allergy (1 paper, 2020). "T‐cell cross‐reactivity has recently been demonstrated for nut allergy, where cashew‐specific CD4+ T cells from cashew‐allergic subjects can cross‐react with tree nut allergens such as hazelnut and pistachios due to homologous T‐cell epitopes with high amino acid identity." (PMID 32436591, 2020).
Nystagmus (1 paper, 2012). Rhythmic, involuntary oscillations of one or both eyes related to abnormality in fixation, conjugate gaze, or vestibular mechanisms. "Among HIV+ participants, the presence of gaze-evoked nystagmus was unrelated to CD4+ or CD8+ T cell counts, or use of antiretroviral medications." (PMID 22675462, 2012).
ocular tuberculosis (1 paper, 2013). Tuberculous infection of the eye, primarily the iris, ciliary body, and choroid. "CD4+ cell counts in patients with ocular tuberculosis were between 14 to 560 cells/μl (mean, 160.85 cells/μl)." (PMID 23514612, 2013).
Opsoclonus (1 paper, 2013). "Our case is unique since the patient had an elevated CD4 count and negative viral load in the period when the opsoclonus-myoclonus-ataxia syndrome occurred." (PMID 24488398, 2013).
optic neuritis (1 paper, 2018). Optic neuritis is inflammation of the optic nerve, the nerve that carries the visual signal from the eye to the brain.The conditionmay cause sudden, reduced vision in the affected eye(s). "The lack of spontaneous EAE or optic neuritis in 2D2xCD19-BMHCIIxIgHMOG mice is in agreement with the previously reported limitations for B cells to prime CD4 T cells." (PMID 29944721, 2018). "Hence, the responsibility for CD4 T cell activation and initiation of demyelination in spontaneous EAE most likely falls on DCs, which have been found to be capable of independently initiating spontaneous optic neuritis." (PMID 29944721, 2018).
oral cavity cancer (1 paper, 2022). A primary or metastatic malignant neoplasm involving the oral cavity. "Actually, a meta-analysis about the prognostic significance of CD4+ and CD8+ tumor-infiltrating lymphocytes in oral cavity cancers showed that the prognostic relevance depends on their intra-tumoral location." (PMID 36713516, 2022).
oral mucositis (1 paper, 2024). Inflammation of the mucous membranes of any of the structures in the mouth. "They found that the administration of the probiotics resulted in a decrease in the incidence and severity of oral mucositis, an increase in the CD3, CD4, CD8 T-cells and lymphocyte levels." (PMID 39359935, 2024).
orbital disease (1 paper, 2026). "Notably, it reduced key signs of orbital disease, including brown adipose tissue expansion, CCL5-positive immune cell infiltration, CD4+ T-cell infiltration and the presence of F4/80+ macrophages." (PMID 41837138, 2026).
orchitis (1 paper, 2020). Inflammation of one or both testes due to viral or bacterial infections. "It is reasonable to assume that the decreased number of CD4+ Tregs in the chronic phase of orchitis outnumbers the increased number of CD8+ Tregs, thus representing an overall decrease." (PMID 33374605, 2020). "In vasectomized mice, CD4+CD25+ Tregs mediated immune tolerance to meiotic germ cell antigens (MGCA), which egressed from normal tubules, while depletion resulted in MGCA-specific autoimmune response and bilateral orchitis." (PMID 33374605, 2020).
Osteochondroma (1 paper, 2017). A common, benign cartiliginous neoplasm arising from the metaphysis of bone. "Since the majority of cells that express CD4 are T cells, we tested whether deletion of Erk2 in the T cells induced osteochondromas by removing the T cells in DKOCD4 mice." (PMID 28507546, 2017). "The fact that osteochondromas only developed in DKOCD4 mice, but not mice that only lack Erk2 in CD4-expressing cells, suggests that the chondrocytes must also lack Erk1 in order for osteochondromas to form." (PMID 28507546, 2017).
otorrhea (1 paper, 2011). "In an earlier study from our unit, the prevalence of otorrhea before the widespread availability of ART was 32%, close to the prevalence in our deferred-therapy group, and was linked to CD4 depletion." (PMID 22029910, 2011). "Overall, median CD4 count increased from 1255 cells per mm3 pre-otorrhea to 1352 afterwards: in the deferred group, CD4 count decreased from 1286 to 1160; in the early group, CD4 count increased from 1213 to 1774 cells per mm3." (PMID 22029910, 2011). "In this prospective randomized study, we showed that early initiation of ART provided significant protection against otorrhea compared to deferred ART, initiated on the basis of either CD4 depletion or progression of HIV disease." (PMID 22029910, 2011). "Had we included infants with a CD4 percentage below 25% in CHER, it is likely that we would have documented a higher prevalence of otorrhea." (PMID 22029910, 2011).
otosclerosis (1 paper, 2020). Formation of spongy bone in the labyrinth capsule which can progress toward the stapes (stapedial fixation) or anteriorly toward the cochlea leading to conductive, sensorineural, or mixed hearing loss. "In immunohistochemical examinations, the determination in otosclerosis foci of CD3+, CD4+ and CD8+ T lymphocyte cells, complementary fragments and β2 microglobulin, has been evaluated as evidence of the inflammatory mechanism of otosclerosis." (PMID 30926454, 2020).
ovarian liposarcoma (1 paper, 2025). "Primary ovarian liposarcoma is extremely rare in clinical practice and is typically diagnosed through lesion biopsy or postoperative pathology combined with immunohistochemistry and FISH results (e.g., MDM2 positive, CD4 positive, etc.)." (PMID 41450911, 2025).
overlap syndromes (1 paper, 2025). "Reports have documented cases of overlap syndromes involving IgG4-RD and AAV, highlighting shared pathogenic mechanisms that may include macrophages, B cells, CD4+T cells, and inflammatory cytokines." (PMID 41181091, 2025). "Despite shared features such as B-cell maturation, CD4+T-cell differentiation, macrophage activation, and cytokine secretion, the pathophysiological mechanisms linking IgG4-RD and AAV overlap syndrome remain unclear." (PMID 41181091, 2025).
panhypopituitarism (1 paper, 2025). Insufficient production of all the anterior pituitary hormones. "Laboratory evaluation demonstrated a positive rapid plasma reagin (RPR) test at 1:64, a CD4 count of 391 cells/μL, a viral load of 40,000 copies/mL, and biochemical evidence of panhypopituitarism." (PMID 41438255, 2025).
panic disorder (1 paper, 2022). An anxiety disorder characterized by multiple unexpected panic attacks with persistent concern of recurring attacks. "Conversely, a separate study of only patients with panic disorder showed decreased CD8 + T cells and a related increase in CD4 + /CD8 + T cell ratio." (PMID 35092543, 2022).
paroxysmal AF (1 paper, 2015). "To explore the surface expression characteristics of PD-1/PD-L on peripheral blood cells, we firstly detected PD-1 expression on CD4+ and CD8+ T cells in paroxysmal AF patients, persistent AF patients and control group." (PMID 25810125, 2015).
pars planitis (1 paper, 2016). An inflammatory disorder of the cilliary body in the uvea that affects healthy, younger individuals who are often asymptomatic. "The exact cause of pars planitis remains unknown, but CD4+ T cells that express an activation marker CD69 (an early activation marker) in either peripheral blood or in the aqueous humor are found, respectively, in patients with pars planitis and with idiopathic uveitis." (PMID 26438050, 2016).
Peri-Implantitis (1 paper, 2024). An inflammatory process with loss of supporting bone in the tissues surrounding functioning DENTAL IMPLANTS. "In contrast, peri-implantitis in the medium- and high-risk groups exhibited a significant increase in CD4+ T cells." (PMID 39555067, 2024). "In peri-implantitis, activated CD4+ T cells dominate the inflammatory infiltrate." (PMID 39555067, 2024).
periapical granuloma (1 paper, 2021). Chronic nonsuppurative inflammation of periapical tissue resulting from irritation following pulp disease or endodontic treatment. "Immunohistochemical stainings showed that CD4+ helper and CD8+ cytotoxic T lymphocytes, along with CD20+ B lymphocytes and CD68+ macrophages, were diffusely distributed in all periapical cysts and in some periapical granulomas, but CD79α+ plasma cells characterized especially periapical granulomas." (PMID 34441046, 2021).
peritoneal neoplasm (1 paper, 2023). A benign or malignant neoplasm that affects the peritoneal cavity. "It was also found the peritoneal neoplasms patients presented with higher levels of circulating CD3 + CD4 + T cells, CD3 + CD8 + T cells, PD-1 + T lymphocytes, PD-1 + CD4 + T cells and PD-1 + CD8 + T cells, compared with health control." (PMID 36991376, 2023). "Compared with normal control, the percentages of CD3 + CD4 + T cells and CD3 + CD8 + T cells were increased in the peripheral blood with peritoneal neoplasms patients (p = 0.004, p = 0.047)." (PMID 36991376, 2023). "We also investigated the frequencies of PD-1 and Tim-3 on circulating Lymphocytes, CD3 + T cells, CD3 + CD4 + T cells and CD3 + CD8 + T cells if would correlate with the progression-free survival of peritoneal neoplasms patients." (PMID 36991376, 2023). "We compared the differential percentages of PD-1 and Tim-3 on circulating lymphocytes, CD3 + T cells, CD3 + CD4 + T cells and CD3 + CD8 + T cells between primary peritoneal neoplasms group compared with secondary group by flow cytometry.." (PMID 36991376, 2023). "The percentages of CD45 + PD-1 + lymphocytes, CD3 + PD-1 + T cells, CD3 + CD4 + PD-1 + T cells in peripheral blood were not correlated with the different primary sites in secondary peritoneal neoplasms group (p > 0.05)." (PMID 36991376, 2023). "We hypothesized that peripheral blood analyses of PD-1 and Tim-3 expressed on lymphocytes, CD3 + T cells, CD3 + CD4 + T cells and CD3 + CD8 + T cells would provide new insights about the mechanism of peritoneal neoplasms progression." (PMID 36991376, 2023). "Our data showed the percentages of CD45 + PD-1 + lymphocytes, CD3 + PD-1 + T cells, and CD3 + CD4 + PD-1 + T cells were increased in the secondary peritoneal neoplasms group, compared with primary group, while Tim-3 had no statistical differences." (PMID 36991376, 2023). "Tim-3 had no statistical differences in primary peritoneal neoplasms group compared with secondary group (p > 0.05), but CD45 + Tim-3+% lymphocytes, CD3 + Tim-3+%T cells, and CD3 + CD4 + Tim-3 + T cells were associated with different secondary sites of peritoneal neoplasms (p < 0.05)." (PMID 36991376, 2023). "Therefore, in the present study, we explored peripheral PD-1 and Tim-3 expressed on circulating lymphocytes, CD3 + T cells, CD3 + CD4 + T cells and CD3 + CD8 + T cells whether to associate with primary sites and pathological types of peritoneal neoplasms or not." (PMID 36991376, 2023).